HTT (huntingtin)
Diseases named in the same sentence as HTT in open-access papers (continued):
Sharing a sentence is not in itself a finding about the gene and the disease.
Huntington disease (continued). "In the context of Huntington disease (HD), which is caused by polyglutamine expansions in HTT, both Rab3 levels and the conversion from GTP to GDP state are dysregulated, which is consistent with a role for HTT in the transport of SVPs." (PMID 37431882, 2023). "The second disorder is Huntington disease (HD), which is caused by a mutation of the N-terminal polyglutamine in the huntingtin protein (mHTT) that induces damage to the brain’s striatum." (PMID 37686127, 2023). "Splicing of the HTT huntingtin gene, which contains a CAG repeat, is altered at expanded repeats associated with Huntington’s Disease, resulting in the production of a transcript containing only exon 1 and the production of an exon 1 HTT protein." (PMID 36940239, 2023). "Numerous REDs are caused by CAG repeats, including the huntingtin gene in Huntington’s disease (HD) and Ataxin 3 in spinocerebellar ataxia type 3 (SCA3), with toxicity largely attributed to the aggregation of long polyQ containing proteins." (PMID 36940239, 2023). "Huntington’s disease (HD) is a neurodegenerative disorder caused by the expansion of CAG trinucleotide repeats in the Huntingtin (HTT) gene." (PMID 37637962, 2023). "Huntington’s disease (HD) is caused by a CAG repeat expansion in the Huntingtin gene (HTT) on chromosome 4, which codes for polyglutamine in the Huntingtin protein (Htt)." (PMID 37744022, 2023). "Huntington’s disease (HD) is caused by a dominantly inherited CAG repeat expansion in exon 1 of the huntingtin gene (HTT), which can be removed through CRISPR-Cas9-mediated fragment deletion in patient-derived fibroblasts and mouse models." (PMID 37051232, 2023). "Huntington’s disease (HD) is a neurodegenerative disorder caused by expanded (≥ 40) glutamine-encoding CAG repeats in the huntingtin gene, which leads to dysfunction and death of predominantly striatal and cortical neurons." (PMID 37353500, 2023). "Huntington disease is an incurable degenerative disorder caused by a mutation in the huntingtin gene, where the CAG sequence is excessively repeated." (PMID 37108382, 2023). "Huntington’s disease (HD) is a movement disorder caused by a mutation in the Huntingtin gene that leads to severe neurodegeneration." (PMID 37580082, 2023). "Huntington’s disease (HD) is caused by the expansion of a polyglutamine (polyQ)-encoding tract in exon 1 of the huntingtin gene to greater than 35 CAG repeats." (PMID 37623904, 2023). "Huntington’s disease (HD) is an autosomal dominant neurodegenerative disease caused by the expansion of the CAG repeat in the huntingtin (HTT) gene, resulting in a poly-glutamine tract in the translated protein." (PMID 39165755, 2023). "Huntington’s disease is a neurodegenerative disease caused by the presence of CAG triplet in the huntingtin gene that ultimately causes alterations in [Ca2+]i homeostasis with synaptic dysfunction and consequent neurodegeneration." (PMID 37298129, 2023). "Protein misfolding and aggregation play central roles in the pathogenesis of various neurodegenerative diseases (NDDs), including Huntington’s disease, which is caused by a genetic mutation in exon 1 of the Huntingtin protein (Httex1)." (PMID 38016971, 2023). "Huntington disease (HD) is a neurodegenerative disorder caused by expanded CAG repeats in the huntingtin gene that alters cellular homeostasis, particularly in the striatum and cortex." (PMID 36590162, 2023). "Huntington's disease is an autosomal-dominant neurodegenerative disease caused by the expansion of CAG repeats in the Huntingtin (htt) gene." (PMID 36991462, 2023). "A hallmark of Huntington’s disease (HD) is a prolongedpolyglutaminesequence in the huntingtin protein and, correspondingly, an expandedcytosine, adenine, and guanine (CAG) triplet repeat region in themRNA." (PMID 37062072, 2023). "Huntington’s disease, caused by a mutation in the huntingtin (HTT) gene, has been explored for AAV-based gene silencing with miRNAs targeting HTT." (PMID 36992407, 2023).
Huntington disease (continued). "Huntington’s disease (HD) is a neurodegenerative autosomal dominantly inherited disorder caused by a mutation of the Huntingtin gene located in chromosome 4." (PMID 38001993, 2023). "Huntington disease is caused by an abnormal expansion of CAG repeats (full-penetrance pathogenic repeat number [same hereafter]: ≥ 39) in the Huntingtin (HTT) gene on 4p16.3." (PMID 36169768, 2023). "Huntington’s disease (HD) is a progressive neurodegenerative disease caused by a CAG repeat expansion at the exon 1 location of the huntingtin (HTT) gene." (PMID 37117485, 2023). "Huntington’s disease (HD) is an autosomal dominant neurodegenerative disorder caused by CAG repeat expansions in the huntingtin gene (HTT), leading to degeneration initially in the striatum that spreads to cortical areas in the brain." (PMID 37259916, 2023). "Huntington’s disease (HD) is a progressive neurodegenerative disorder caused due to a CAG repeat expansion in the huntingtin (HTT) gene." (PMID 37761940, 2023). "Huntington's disease (HD) is primarily caused by the enlargement of the trinucleotide repeat (CAG) inside the huntingtin gene (HTT) located on chromosome 4." (PMID 38021751, 2023). "Huntington’s disease (HD) is caused by a mutation in the huntingtin (HTT) protein that leads to protein misfolding and aggregation." (PMID 38213543, 2023). "For example, pathological accumulation of alpha-synuclein in Parkinson’s disease or the mutated huntingtin protein in Huntington’s disease triggers HSF1 degradation." (PMID 36610605, 2023). "Huntington’s disease (HD) is a neurodegenerative disorder caused by CAG-repeat expansions in the huntingtin (HTT) gene." (PMID 37407555, 2023). "Huntington's disease (HD) is a progressive neurodegenerative disorder caused by inheriting a defected huntingtin gene." (PMID 37277696, 2023). "The pathogenic fragment of polyQ-expanded exon 1 of mutant HTT in different model organisms and human cells is sufficient to recapitulate key aspects of Huntington’s disease, including pathological protein aggregation and cell death." (PMID 37783816, 2023). "Huntington’s disease (HD) is caused by expanded CAG repeats in the huntingtin gene (HTT) and is characterized by late-onset neurodegeneration that primarily affects the striatum." (PMID 37539389, 2023). "Huntington’s disease (HD) is an autosomal dominant neurodegenerative disease caused by CAG trinucleotide repeat expansions in exon-1 of huntingtin (HTT)." (PMID 36262216, 2023). "We demonstrate that aggregates of mutant huntingtin (mHtt), the disease-causing agent of Huntington’s disease can be artificially targeted to daughter cells as well as to eisosomes and endosomes with this approach." (PMID 37160881, 2023). "Huntington’s disease is caused by cytosine-adenine-guanine (CAG) expansion which encodes a polyglutamine at the N-terminus of huntingtin (HTT)." (PMID 37107583, 2023). "Huntington’s disease (HD) is a progressive inherited neurodegenerative disease caused by a CAG repeat expansion in the huntingtin gene, which is translated into the pathologic mutant huntingtin (mHTT) protein." (PMID 36839842, 2023). "Huntington's disease (HD) is an autosomal dominant genetic disorder caused by a CAG triplet expansion in the huntingtin gene (HTT), encoding an expanded polyglutamine (polyQ) tract near the N-terminus of the HTT protein." (PMID 36782185, 2023). "HTT protein mutation causes the impaired removal of dysfunctional mitochondria by mitophagy, and is related with the development of Huntington disease (HD)." (PMID 38069199, 2023). "Huntington's disease (HD) is caused by an elongated CAG triplet repeat expansion in exon 1 of the Huntingtin gene in chromosome 4." (PMID 36717864, 2023). "Huntington’s Disease (HD) is a neurodegenerative disease caused by a cytosine–adenine–guanine (CAG) triplet expansion mutation in exon 1 of huntingtin gene (HTT) responsible for the degeneration of striatal neurons in the brain." (PMID 36978821, 2023).
Huntington disease (continued). "Huntington’s disease (HD) is an autosomal dominant hereditary neurodegenerative disorder caused by CAG repeat expansion in the huntingtin (HTT) gene encoding the HTT protein." (PMID 36827300, 2023). "Huntington’s Disease (HD) is a herditary neurodegenerative disorder that arises due to elongated CAG repeats in the gene that encodes the Huntingtin protein." (PMID 36915214, 2023). "Huntington’s disease (HD) is a monogenic dominant neurodegenerative condition caused by the expansion of the CAG trinucleotide repeat tract at the 5′ end of the Huntingtin (HTT) gene." (PMID 37507794, 2023). "Huntington’s disease (HD) is a rare neurodegenerative disorder caused by a CAG repeat expansion in the coding region of the huntingtin gene." (PMID 37501188, 2023). "The CAG repeat sequences in huntingtin (HTT) gene have been reported to cause Huntington’s disease (HD)." (PMID 36833410, 2023). "Huntington disease (HD) is a neurodegenerative disorder caused by an expanded polyglutamine (CAG) trinucleotide expansion in the huntingtin (HTT) gene that encodes the mutant huntingtin protein (mHTT)." (PMID 37591545, 2023). "Huntington’s disease (HD) is a neurodegenerative disorder caused by a dominant gain-of-function mutation in the huntingtin gene, resulting in an elongated polyglutamine repeat in the mutant Huntingtin (mHtt) that mediates aberrant protein interactions." (PMID 38081944, 2023). "Huntington’s disease (HD) is a neurodegenerative disorder caused by a dominantly inherited CAG repeat expansion in the huntingtin gene (HTT)." (PMID 37993517, 2023). "Huntington’s disease (HD) is caused by a dominant mutation in the huntingtin (HTT) gene, which consists of an abnormal expansion of a gene’s CAG repeat." (PMID 37623904, 2023). "Huntington’s disease (HD) is a disorder caused by an abnormal expansion of trinucleotide CAG repeats within the huntingtin (Htt) gene." (PMID 37446028, 2023). "Huntington’s disease (HD) is a fatal neurodegenerative disorder caused by the expansion of a CAG trinucleotide repeat in the Huntingtin gene." (PMID 37569316, 2023). "Huntington's disease (HD) is a devastating neurodegenerative disorder caused by an aberrant expansion of CAG triplets in the HTT (Huntingtin) gene [...]." (PMID 36901739, 2023). "Huntington’s Disease (HD) is a progressive neurodegenerative disease caused by CAG repeat expansion in the huntingtin gene (HTT)." (PMID 36902304, 2023). "Huntington’s disease (HD) is a neurodegenerative disorder caused by a CAG repeat expansion in the N-terminus of the HTT gene." (PMID 36926679, 2023). "Huntington’s disease (HD): HD is caused by a mutation in the huntingtin gene, resulting in the accumulation of a toxic mutant huntingtin protein in neurons." (PMID 37681887, 2023). "Huntington disease (HD) is an autosomal dominant neurodegenerative disorder caused by an expanded polyglutamine (CAG) repeat in exon 1 of the huntingtin (HTT) gene." (PMID 37591545, 2023). "Huntington’s disease (HD) is an autosomal dominant inherited neurodegenerative disease caused by mutations in the huntingtin (Htt)-encoding gene (HTT)." (PMID 37047151, 2023). "Huntington’s disease is caused by a CAG repeat expansion in the Huntingtin gene (HTT), coding for polyglutamine in the Huntingtin protein, with longer CAG repeats causing earlier age of onset." (PMID 37744022, 2023). "Huntington’s disease (HD) is a debilitating neurodegenerative genetic disorder caused by an expanded polyglutamine-coding (CAG) trinucleotide repeat in the huntingtin (HTT) gene." (PMID 37629202, 2023). "Huntington’s disease (HD) is an inherited autosomal dominant neurodegenerative disease caused by CAG repeats in exon 1 of the HTT gene." (PMID 37415834, 2023). "Huntington’s disease (HD) is an autosomal dominant neurodegenerative disorder caused by an increase in ≥36 CAG repeats in the HTT gene encoding the polyglutamine segment of the huntingtin protein (phenotype MIM 143100)." (PMID 36614266, 2023).
Huntington disease (continued). "Huntington’s disease (HD) is a fatal neurodegenerative disorder caused by a genetic mutation in the huntingtin gene (HTT)." (PMID 36754966, 2023). "Huntington’s disease (HD) is a severe neurodegenerative disorder caused by the expansion of the CAG trinucleotide repeat tract in the huntingtin gene." (PMID 37177784, 2023). "Huntington’s disease (HD) is a fatal neurodegenerative disorder caused by a polyglutamine (polyQ) repeat expansion in the HTT gene." (PMID 37415834, 2023). "Huntington Disease (HD) is an autosomal-dominant progressive neurodegenerative disease caused by a mutation in the HTT gene." (PMID 37324388, 2023). "Huntington's disease (HD) is a genetic disorder caused by a CAG trinucleotide expansion in the huntingtin (HTT) gene." (PMID 38003344, 2023). "Huntington’s disease (HD) is an autosomal dominant neurodegenerative disease (recently reported peripheral tissue involvement) caused by genetic mutation in the huntingtin gene (HTT) that leads to tandem CAG repeats." (PMID 36671411, 2022). "Huntington’s disease (HD) is a neurodegenerative disorder caused by poly-Q expansion in the Huntingtin (HTT) protein." (PMID 36357392, 2022). "IPA upstream analysis also suggested inhibition of transcriptional regulator HTT (huntingtin; Z = −2.381, p < 0.001) primarily associated with the Huntington’s disease." (PMID 36552881, 2022). "Huntington’s disease (HD) is caused by an expansion of the CAG trinucleotide repeat domain in the huntingtin gene that results in expression of a mutant huntingtin protein (mHTT) containing an expanded polyglutamine tract in the amino terminus." (PMID 35395060, 2022). "Huntington’s disease (HD) is a neurodegenerative disorder caused by an abnormal expansion of a glutamine tract (polyQ) near the N-terminus of huntingtin (HTT) protein." (PMID 35853002, 2022). "Huntington’s disease (HD) is caused by an expanded CAG trinucleotide repeat in the first exon of the huntingtin gene (HTT)." (PMID 36040815, 2022). "Huntington’s Disease (HD) is an inherited neurodegenerative disease caused by the expansion of CAG repeats in the huntingtin gene." (PMID 35207662, 2022). "Huntingtin (Htt), a hallmark protein of Huntington’s disease, has been observed to cross-seed and promote the fibrillation of TIA-1, an RNA-binding protein rich in glutamine and asparagine residues." (PMID 35335141, 2022). "Huntington’s disease (HD) is a devastating neurodegenerative disorder that is caused by an abnormal expansion of CAG repeats in the Huntingtin (HTT) gene." (PMID 35628221, 2022). "Huntington’s disease is caused by the amplification of CAG triplet repeat in the first exon of huntingtin (HTT) gene, resulting in abnormal forms of the protein to clump together and form aggregates in brain cells." (PMID 35359573, 2022). "Genetic mutations can cause a protein to aggregate, e.g., the misfolded Huntingtin protein in Huntington’s disease, which suffers expansion of a poly-glutamine (polyQ) region." (PMID 35409310, 2022). "Huntington’s disease (HD) is an autosomal dominant genetic disorder caused by an expansion of the CAG repeat in the first exon of Huntingtin’s gene." (PMID 35517051, 2022). "Huntington’s disease (HD) is a neurodegenerative disorder with autosomal dominant inheritance caused by glutamine expansion in the Huntingtin gene (HTT)." (PMID 36553652, 2022). "Huntington disease (HD) is an autosomal dominant neurodegenerative disorder caused by an expanded polyglutamine repeat in exon 1 of the gene encoding the huntingtin protein, leading to the expression of mutated huntingtin (mHTT)." (PMID 34531262, 2022). "Huntington disease (HD) is a neurodegenerative disease where a genetic mutation leads to excessive polyglutamine (Q) repeats in the huntingtin protein." (PMID 36180805, 2022). "Huntington’s disease is mainly caused by an autosomal dominant mutation in either of the two copies of the Huntingtin (HTT) gene." (PMID 35668943, 2022).
Huntington disease (continued). "In Huntington’s disease, the expansion of polyQ tracts in huntingtin (Htt) protein is a hallmark of disease." (PMID 35602608, 2022). "Huntington’s disease (HD) is an autosomal-dominant monogenetic neurodegenerative disease caused by a cytosine–adenine–guanine (CAG) trinucleotide repeat expansion in the HTT gene." (PMID 35061089, 2022). "Huntington’s disease is a neurodegenerative disorder caused by CAG repeat expansion in the huntingtin (HTT) gene." (PMID 35743271, 2022). "Huntington’s disease (HD), an autosomal dominant neurodegenerative disorder, is caused by aggregation of mutant huntingtin (mHtt)." (PMID 35589670, 2022). "In order to investigate Huntington’s disease and its pathogenesis, different experimental models were designed that express full-length or N-terminal fragments of mutated HTT." (PMID 36551756, 2022). "In Huntington disease, the aggregation of a mutated protein, named Huntingtin (Htt) depends on the number of Q in the polyQ expansion." (PMID 35409310, 2022). "Huntington’s disease occurs when the stretch of CAG repeats in exon 1 of the huntingtin (htt) gene crosses the permissible limit, causing the mutated protein (mHtt) to form insoluble aggregates or inclusion bodies." (PMID 36425218, 2022). "Yet, investigations into Huntington’s disease—caused by a CAG repeat expansion in exon 1 of the huntingtin (HTT) gene—have primarily focused on toxic protein gain-of-function as the primary disease-causing feature." (PMID 36458209, 2022). "Huntington’s disease is an autosomal dominant neurodegenerative disorder caused by the CAG repeat expansions in the huntingtin (HTT) gene, and clinically manifests as hyperkinetic movement disorder and cognitive decline." (PMID 35805109, 2022). "Huntington disease (HD) is caused by the expansion of CAG triplet repeats in exon 1 of the huntingtin (HTT) gene, which also encodes the first 17 amino acids (N-17) that can modulate the toxicity of the expanded polyQ repeat." (PMID 36439204, 2022). "Huntington’s disease is a progressive neurodegenerative disorder caused by a lethal autosomal dominant mutation in the gene coding for huntingtin (HTT)." (PMID 36551756, 2022). "Huntington’s disease is a neurodegeneration caused by a CAG repeat in the gene encoding HTT protein." (PMID 35359573, 2022). "Huntington’s disease is caused by a pathologically long (>35) CAG repeat located in the first exon of the Huntingtin gene (HTT)." (PMID 34974533, 2022). "Huntington’s disease (HD) is a neurodegenerative disorder that is caused by a CAG trinucleotide repeat expansion in exon 1 of the huntingtin (HTT) gene, which results in the production of abnormal proteins that gradually damage brain cells." (PMID 36135023, 2022). "Huntington’s disease (HD) is a neurodegenerative disorder whereby mutated huntingtin protein (mHTT) aggregates when polyglutamine repeats in the N-terminal of mHTT exceeds 36 glutamines (Q)." (PMID 35305696, 2022). "Here, we report that SETD2 deficiency was found to be associated with decreased turnover of mutant-HTT protein and increased cellular toxicity, offering a novel link to Huntington disease." (PMID 36371383, 2022). "Huntington’s disease (HD) is a neurodegenerative disorder with a genetic inherent caused by glutamine expansion in the Huntingtin gene (HTT) on chromosome 4." (PMID 36553652, 2022). "Huntington’s disease (HD) is caused by a mutant huntingtin (mHTT) protein that contains abnormally extended polyglutamine (polyQ) repeats." (PMID 36187470, 2022). "The TRACK-HD study in 2009 used multi-site MRI to show quantifiable biological and clinical alternation in Huntingtin mutation carriers compared with age-matched controls demonstrating the feasibility of using this technique to detect Huntington's disease." (PMID 35651462, 2022).